RNU6-158P (RNA, U6 small nuclear 158, pseudogene)
Gene: Small nuclear RNA gene on chromosome 4 (48,932,755 to 48,932,854, reverse strand). Ensembl gene ENSG00000252913.
Homologues: Orthologues: chimpanzee U6 (100% identical), macaque U6 (92% identical), rabbit U6 (66% identical), dog U6 (62% identical), guinea pig U6 (60% identical), mouse Gm55537 (59% identical), rat LOC120099619 (57% identical). Paralogues in human: RNU6-641P (76% identical), RNU6-949P (76% identical), RNU6-356P (75% identical), RNU6-738P (75% identical), RNU6-1318P (74% identical), RNU6-21P (74% identical), RNU6-345P (74% identical), RNU6-80P (74% identical), RNU6-1082P (73% identical), RNU6-1125P (73% identical), RNU6-128P (73% identical), RNU6-1292P (73% identical), and 1281 more.